BCL2 (BCL2 apoptosis regulator)
Diseases named in the same sentence as BCL2 in open-access papers (continued):
Sharing a sentence is not in itself a finding about the gene and the disease.
injury (24 papers, 2010 to 2026). Damage inflicted on the body as the direct or indirect result of an external force, with or without disruption of structural continuity. "A series of studies have shown that DEX can reverse the increase in Bax and the decrease in Bcl-2 after nerve injury and inhibit the level of caspase-3, thus alleviating apoptosis after nerve injury." (PMID 36204225, 2022). "Our findings are consistent with the previous study, showing that Nec-1 increased hippocampal Bcl-2 and decreased hippocampal cleaved caspase-3 in mice with traumatic brain injury." (PMID 34689160, 2021). "Previous studies showed that caspase-3 activity was significantly increased and Bcl-2 expression was significantly decreased after IR-induced lung injury." (PMID 34658893, 2021). "For example, following brain injury, over-expression of Bcl2 has been found to increase activation of neural progenitor cells and reduce apoptosis of newly formed neurons." (PMID 24423034, 2014). "It has previously been suggested that Bcl-2 and Bax plays a pivotal role in inducing mitochondria-mediated apoptosis in glomerular diseases and ischemic and toxic kidney injury." (PMID 22389723, 2012). "The Nrf2/HO-1 pathway could reverse apoptotic reactions, inflammation, and oxidative stress damages as evidenced by elevated SOD and Bcl-2 levels and reduced Bax expression in acute lung injury." (PMID 37529170, 2023). "Moreover, TA was found to inhibit inflammatory response and apoptosis through attenuation of TNF-α, IL-1β, IL-6, Bax, Bcl-2, and caspase-3 in CCl4-induced liver injury in mice." (PMID 36358896, 2022). "The most common mechanisms for upregulating the autophagic flux after traumatic brain injury include the following: increased levels of Beclin 1 protein and a decrease in the Beclin-1/BCL2 complex; enhanced type-III PI3 kinase activity; and autophagic processes." (PMID 34738222, 2022). "Materials and Methods: All studies in English were queried from the National Library of Medicine PubMed database using the following search terms: (B-cell lymphoma 2/Bcl-2/Bcl2) AND (brain injury/head injury/head trauma/traumatic brain injury) AND (human/patient/subject)." (PMID 32570722, 2020). "Notably, in children following head trauma increased levels of soluble BCL2 protein in spinal fluid correlated with improved survival." (PMID 20161703, 2010). "A recent study showed that besides the antiapoptotic function of Bcl2, its overexpression inhibits mitophagy via modulating the PINK1/Parkin pathway in a model of acute lung injury." (PMID 35814769, 2022).
lymph node metastasis (23 papers, 2003 to 2025). "In particular, patients with colorectal adenocarcinoma without p-Bcl-2 (Ser70) expression exhibit shorter survival rates than patients with positive p-Bcl-2 (Ser70) expression, which is correlated with lymph node metastasis and clinical stages." (PMID 34391437, 2021). "Patients with elevated expression of Bcl2 and c-Met tend to have lymph node metastasis (P = 0.000, P = 0.001), advanced stage (P = 0.00)." (PMID 28615991, 2017). "The expression levels of Bcl-2, Twist1, E-cadherin, N-cadherin, Vimentin and MMP-2/9 were significantly associated with lymph node metastasis, and the differences in the pathologic grades were significant." (PMID 28032603, 2017). "Significant correlations were found between Bcl-2 and deep invasion (p = 0.033), survivin and lymph node metastasis (p = 0.006), as well as cyclin D1 and clinical stage (p = 0.014)." (PMID 25438156, 2014). "There was a negative correlation between the positive expression rate of BCL-2 and histologic grade or the lymph node metastasis (P < 0.05)." (PMID 20691103, 2010). "Bcl-2—The negative expression of Bcl-2 is associated with an increased chance of cancer recurrence, lymph node metastases, and depth of invasion." (PMID 39335135, 2024). "The IL-1RN rs419598 wild-type genotype was significantly related to stage III-IV disease, the PIGR rs291102 wild-type genotype was significantly related to normal levels of CYFRA, and the BCL2 rs2279115 wild-type genotype was significantly related to lymph node metastasis." (PMID 34150619, 2021). "The IL-1RN rs419598 wild-type genotype was significantly related to stage III-IV disease, the PIGR rs291102 wild-type genotype was significantly related to normal levels of cytokeratin fragment 19 (CYFRA), and the BCL2 rs2279115 wild-type genotype was significantly related to lymph node metastasis." (PMID 34150619, 2021). "Depth of invasion, lymph node metastases, and negative expression of bcl-2 predict greater risk of recurrence." (PMID 24555747, 2014). "Depth of invasion, lymph node metastases, and negative expression of bcl-2 were independent risk factors for overall recurrence." (PMID 24555747, 2014). "In our experiment, we analyzed correlation between the expression pattern of Beclin1, ULK1, bcl2 and LC3 with clinical and pathological features (subtype, stage, lymph node metastasis and smoking)." (PMID 33773561, 2021). "It was demonstrated that depth of invasion, lymph node metastases, and negative expression of bcl-2 were independent predictive factors for overall recurrence." (PMID 24555747, 2014). "The stage, curability, T-factor, lymph node metastasis, tumor thrombus in the portal vein, intrahepatic metastasis, and carbohydrate antigen 19-9 (CA19-9) were found to be significant prognostic factors for overall survival, as well as the SSTR2 and Bcl2 expression pattern (p-Group H and U)." (PMID 33962620, 2021).
malignant glioma (23 papers, 1998 to 2025). A grade III or grade IV glioma arising from the central nervous system. "Numerous studies have also demonstrated that Bcl-2 overexpression is associated with resistance to conventional radiation and chemotherapeutic agents in the majority of tumor cells, including malignant glioma cells." (PMID 26043756, 2015). "For example, gossypol, a pan-Bcl-2 inhibitor, was reported to trigger autophagic cell death in malignant gliomas." (PMID 35831271, 2022). "The overexpression of the anti-apoptotic protein B-cell lymphoma 2 (Bcl-2) is considered to be an important factor in the generation, metastasis and angiogenesis of a variety of malignant tumours, including malignant glioma." (PMID 25667663, 2015). "In the present study, chemical hypoxia was used to induce a hypoxic environment for human malignant glioma U87 cells, and the effects of the Bcl-2-specific inhibitor ABT-737 on the VM formation of the U87 cells was subsequently observed." (PMID 25667663, 2015). "Overexpression of anti-apoptotic BCL-2 proteins can confer apoptotic resistance in malignant glioma." (PMID 23691145, 2013). "Apoptosis is a recognised feature of malignant glioma, but the relationship of bcl-2 expression to this is unclear." (PMID 12085183, 2002). "In addition, we have unveiled a tumour promoting role of CFTR in malignant gliomas via up‐regulation of Akt/Bcl2‐mediated anti‐apoptotic pathway." (PMID 32463592, 2020). "Collectively, these results suggest that inhibition of XPO1 and Bcl-2/Bcl-xL might be a potential strategy for the treatment of malignant glial tumors." (PMID 30337641, 2018). "In addition, the pan-Bcl2 inhibitor (−)-gossypol efficiently potentiates caspase-independent autophagic cell death in apoptosis-resistant malignant glioma cells, and it further augments the action of TMZ." (PMID 26830677, 2016). "In conclusion, Bcl-2 may be an important factor in the VM formation of human malignant glioma U87 cells under hypoxic conditions." (PMID 25667663, 2015).
MALT lymphoma (23 papers, 2006 to 2026). An indolent, extranodal type of non-Hodgkin lymphoma composed of small B-lymphocytes (centrocyte-like cells). "The intra- and post-operative courses were unremarkable, but pathology review revealed immunohistochemistry positive for CD20 and BCL-2 with a Ki67 proliferation index of 5%, which was diagnostic of extranodal marginal zone MALT lymphoma of the gallbladder." (PMID 37033512, 2023). "The biopsy specimen demonstrated the dominance of lymphoid cells and tested positive for CD20, CD79a, Bcl-2, and IRTA-1, which is consistent with the findings in MALT lymphoma." (PMID 38694936, 2024). "In immunohistochemistry, MALT lymphoma cells are CD20+, CD79a+, BCL2+, BCL6−, CD5−, CD10−, and CD23−." (PMID 35053607, 2022). "Immunophenotypically, MALT lymphoma cells are CD20+, CD79a+, BCL2+, and IgM+." (PMID 40831827, 2025). "Absence of GC markers, lack of BCL2-rearrangement (R) by FISH, and the presence of a CD79b variant without canonical FL mutations were more consistent with a MALT lymphoma infiltrating duodenum." (PMID 40616614, 2025). "The tumor of maximal 1.0 cm in diameter was consisted of aggregation of lymphocytes of predominantly B-cell, containing multiple lymphocyte follicles positive for CD10 and bcl-2, consistent with a diagnosis of HPL, but still necessitating differential diagnosis from MALT lymphoma." (PMID 21232116, 2011). "One case of MALT lymphoma was diagnosed in a 58-year-old man who presented with stage I disease, with negative CD10, MUM1 and BCL2, suggesting the non-GCB phenotype." (PMID 28086220, 2017). "In contrast, MALT lymphoma is negative for CD10 and only occasionally positive for BCL2." (PMID 25002984, 2014). "Liver tumor of maximal 1.0 cm in diameter was consisted of aggregation of lymphocytes of predominantly B-cell, containing multiple lymphocyte follicles positive for CD10 and bcl-2, consistent with a diagnosis of HPL rather than MALT lymphoma, although a definitive differentiation was pending." (PMID 21232116, 2011).
mesothelioma (22 papers, 2009 to 2025). A usually malignant and aggressive neoplasm of the mesothelium which is often associated with exposure to asbestos. "The expression of Bax/Bcl-2 was seen to exhibit a significant rise of 43% following curcumin therapy in the cell lines of mesothelioma, specifically MM-F1 and MM-B1." (PMID 38978121, 2024). "The nanoconstruct targeted EGFR (a mesothelioma overexpression receptor), and the main targets were genes involved in the progression of this cancer, e.g., BCL2, CDK1, and JUN." (PMID 35326459, 2022). "Preclinical studies have been performed in mesothelioma cell lines using direct or indirect targeting of BCL2 and BCL-XL: both in cell lines and in vivo models this treatment was able to induce an apoptotic effect." (PMID 34249695, 2021). "In mesothelioma, overexpression of BCL-2 was found in 20% of cell lines and in 24% of a tumor samples, while the expression of BCL-XL and MCL-1 was identified as a general feature of mesothelioma, suggesting their critical role as pro-survival factors." (PMID 34249695, 2021). "PI3K-AKT pathway is important for the malignancy of mesothelioma, and it can induce anti-apoptotic BCL2 protein." (PMID 32664372, 2020). "Some correlate high BCL2 expression with poor survival, while other indicate good prognosis of mesothelioma patients with high BLC2 expression." (PMID 32664372, 2020). "Both PI3K genes, PIK3CA and PIK3CD, all 3 AKT genes, AKT1, AKT2 and AKT3, as well as BCL2 gene were detected in mesothelium and mesothelioma samples." (PMID 32664372, 2020). "We tested the expression of OCT4/POU5F1, NANOG, SOX2, PI3K-AKT pathway and BCL2 genes and proteins in 65 samples of human mesothelioma and 19 samples of normal mesothelium." (PMID 32664372, 2020). "Bcl-2 and Bcl-xL enhanced the drug resistance of mesothelioma and laryngeal cancer cells because their down-regulation and Bcl-2 inhibitor (HA14-1) increased the cytotoxic effects of cisplatin, gemcitabine, or the combined treatment with 4625 and cisplatin." (PMID 28938696, 2017). "In mesothelioma cells grown in 3D, the baseline expression of the Bcl-2 family members and the response of the Bcl-2 proteins to pro-apoptotic stress differed significantly from that in the same cells in 2D." (PMID 23300762, 2012). "In our previous study using the NCI-H226 spheroid model, we demonstrated an increase of Mcl-1 in mesothelioma spheroids compared to monolayers, indicating that the mesothelioma spheroid model acquired Bcl-2 signaling apoptotic resistance." (PMID 22737246, 2012). "In the present study, we demonstrated an increase of Mcl-1 in spheroids as compared to monolayers, indicating that the 3D mesothelioma spheroid model had acquired Bcl-2 signaling apoptotic resistance as well as multicellular resistance." (PMID 21305058, 2011). "However, BCL2 protein was expressed only in several mesothelium and mesothelioma samples, with lower expression in mesothelioma." (PMID 32664372, 2020). "Indeed, the key role of BCL2/L1 in mesothelioma has been well demonstrated, and the use of pharmacological inhibitors of BCL2 family members is promising." (PMID 26156019, 2015). "4EASO potently diminished eIF4E protein levels, repressed cap-dependent complex formation, selectively reduced eIF4E regulated proteins (ODC and Bcl-2), reduced mesothelioma cell viability, induced apoptosis, and sensitized mesothelioma cells to gemcitabine and pemetrexed." (PMID 24260583, 2013). "For example, BCL2 and BCL-xL antisense treatment facilitates apoptosis in mesothelioma cells, suggesting BCL2/BCL-xL bispecific antisense treatment in combination with cisplatin or gecitabine may result in a more effective therapy of MM." (PMID 21159167, 2010). "In addition, the inhibition of MetAP2 expression in mesothelioma cells leads to cell death and that such apoptosis is avoided in cases where there is overexpression of Bcl-2." (PMID 19703310, 2009). "However, BCL2 gene and protein were downregulated in mesothelioma." (PMID 32664372, 2020).
mesothelioma (continued). "While mesothelioma had downregulated all tested PI3K, AKT and BCL2 genes, p-PI3K was unaltered, p-AKT was upregulated and BLC2 protein was downregulated." (PMID 32664372, 2020). "Thus, a downregulation of BCL2 in mesothelioma could promote cancer." (PMID 32664372, 2020). "In contrast, in mesothelioma cell lines and MPM cancer specimens, the defensive character of Bcl-2 is fewer evident." (PMID 28704484, 2017). "In contrast, in mesothelioma cell lines and MPM cancer samples, the protective character of Bcl-2 is less evident." (PMID 27806086, 2016). "The mesothelioma samples used for testing OCT4, NANOG and SOX2 expression were also used for investigating the expression of phosphorylated (activated) PI3K (Tyr607; p-PI3K), phosphorylated/activated AKT (Ser473; p-AKT) and BCL2." (PMID 32664372, 2020). "Bcl-2 is not commonly expressed in mesothelioma, but down-regulating Bcl-2 in conjunction with Bcl-xL is more effective in inducing apoptosis." (PMID 29342862, 2018). "We detected little changes of Bcl-2 expression levels and the mechanism (C) was not involved in mesothelioma tested." (PMID 28464864, 2017). "According to immunohistochemical analysis, SFT of the pleura is positive for vimentin, CD34, CD99, and Bcl2, which are markers of mesenchymal cells; but it is negative for cytokeratin, which is found in mesotheliomas." (PMID 21958732, 2011). "However, since BCL2 is poorly expressed in normal mesothelium in our study, it is more likely that it is not important for the mesothelioma." (PMID 32664372, 2020).
myelodysplastic syndrome (22 papers, 1998 to 2025). A clonal hematopoietic disorder characterized by dysplasia and ineffective hematopoiesis in one or more of the hematopoietic cell lines. "The JAK2V617F mutation also enforced Mcl-1 transcription to sensitize myelodysplastic syndrome cell lines to apoptosis induced by a Bcl-xL/Bcl-2 inhibitor." (PMID 34773997, 2021). "Bcl-2 inhibition has been shown to be effective in inducing the apoptosis of progenitor cells in patients with high-risk myelodysplastic syndrome and secondary AML." (PMID 31426381, 2019). "Interactions between the novel hypomethylating agent (HMA) thio-deoxycytidine (T-dCyd) and the BCL-2 antagonist ABT-199 (venetoclax) have been examined in human myelodysplastic syndrome (MDS) cells." (PMID 36810553, 2023). "Combining BCL-2 inhibitors (venetoclax) with low-dose, mainly epigenetically active chemotherapy (e.g.azacytidine) modifies the clinical course of myelodysplastic syndromes/AML, especially with low proliferation activity, very positively with significantly improved survival." (PMID 35159956, 2022). "In this work, we investigated the autonomous proliferation, bcl-2 expression and number of apoptotic cells in the bone marrow of patients with confirmed diagnosis of myelodysplastic syndromes (MDS)." (PMID 9744502, 1998). "All types of AML but not myelodysplastic syndromes (MDS) significantly upregulated Bcl-2 compared with healthy bone marrow." (PMID 38424468, 2024).